RNVU1-29 (RNA, variant U1 small nuclear 29)
Synonyms: LOC124904613
Gene: Small nuclear RNA gene on chromosome 1 (146,376,807 to 146,376,970, forward strand). Ensembl gene ENSG00000273768.
Gene Ontology:
Molecular function: pre-mRNA 5'-splice site binding
Biological process: mRNA 5'-splice site recognition
Cellular component: U1 snRNP
Homologues: Paralogues in human: RNU1-1 (100% identical), RNU1-2 (100% identical), RNU1-27P (100% identical), RNU1-28P (100% identical), RNU1-3 (100% identical), RNU1-4 (100% identical), RNVU1-18 (100% identical), U1 (100% identical), RNVU1-28 (99% identical), RNVU1-7 (99% identical), RNVU1-31 (99% identical), RNU1-89P (97% identical), and 134 more.
Diseases named in the same sentence as RNVU1-29 in open-access papers:
RNVU1-29 is named in the same sentence as 1 disease in open-access papers, as found by Europe PMC text mining. Sharing a sentence is not in itself a finding about the gene and the disease.
RNVU1-29 shares sentences with these, for which no sentence is quoted: amyotrophic lateral sclerosis (1 paper).